INS (insulin)
Diseases named in the same sentence as INS in open-access papers (continued):
Sharing a sentence is not in itself a finding about the gene and the disease.
Hypoglycemia (continued). "Peripheral insulin administration as the only strategy for managing diabetic patients with Alzheimer’s disease may increase the risk of hypoglycaemia and hyperinsulinaemia in these patients." (PMID 26193295, 2015). "Results from these studies support the idea of targeting IR for insulin sensitization, which carries low hypoglycemia risk by standalone treatment and could improve the effectiveness of insulin therapies." (PMID 25799496, 2015). "However, concerns around hypoglycemia and other risks associated with self-injection often limit optimal insulin efficacy and prevent patients from achieving ideal glycemic control." (PMID 25799496, 2015). "Because the insulin analogues have shorter durations of action and more rapid onsets of action than regular insulin, they are associated with improved postprandial glycaemic control and less postprandial hypoglycaemia." (PMID 25977899, 2015). "Thus, in the type 1 diabetic patient when an SGLT2 inhibitor is utilized the dose of preprandial short-acting insulin can and should be reduced and on occasion can even be omitted which will reduce the risk of hypoglycemia." (PMID 25785209, 2015). "However, insulin therapy increases the risk of adverse effects, such as hypoglycemia and weight gain." (PMID 25883713, 2015). "Insulin therapy is associated with weight gain and hypoglycemia." (PMID 26157708, 2015). "Indeed, a recent study reported that hypoglycaemia was associated with increased risk of cardiovascular events and all-cause mortality in insulin-treated patients with type 1 diabetes mellitus and T2DM." (PMID 26366172, 2015). "It is possible that for unknown reasons that anti-CD3 treatment leads to enhanced insulin production thereby causing hypoglycemia." (PMID 24741590, 2014). "Hypoglycemia risk may be affected by a variety of treatment-related factors, including type of insulin, route of insulin administration, and SMBG frequency." (PMID 25289645, 2014). "It is well established that glucagon secretion in T1D is impaired, and there is further strong evidence from closed loop delivery systems that bi-hormonal delivery of insulin and glucagon has been shown to reduce the risk of hypoglycaemia when compared with delivery of insulin alone." (PMID 24481872, 2014). "Some antidiabetic drugs, such as insulin, sulfonylureas, and glinides, are associated with relatively high rates of hypoglycemia that may limit their use in some patients." (PMID 24678906, 2014). "The fact that needs to be taken into consideration is that children have a greater risk of hypoglycemia relative to adults, presenting greater sensitivity to the dose of insulin administered and greater daily variability in terms of calorie ingestion and physical activity." (PMID 24790575, 2014). "Currently, several different human insulin formulations and insulin analogs are available commercially, aiming at “personalizing,” as closely as possible, the normal insulin physiology and thereby minimizing its high risk for hypoglycemia." (PMID 25071725, 2014). "Exogenous insulin-induced hypoglycemia is always associated with low levels of C-peptide." (PMID 25038902, 2014). "However, the present findings were consistent with previous reports of hypoglycemia induced by low-dose Mn intake in diabetic patients, as well as changes in insulin metabolism in Mn-deficient animal models." (PMID 24606630, 2014). "However, recent evidence also suggests that it is important for patients to reduce the dose of rapid-acting insulin administered with the meal after exercise as well, so that the risk of post-exercise hypoglycaemia is abated." (PMID 24858952, 2014). "Furthermore, patients had difficulties increasing the insulin dose because they fear hypoglycemia, they associate higher insulin doses with disease progression, and some were ignorant of treatment targets." (PMID 25340869, 2014).
Hypoglycemia (continued). "Current oral insulin formulations reported in the literature are often associated with an unpredictable burst release of insulin in the intestine, which may increase the risk for problematic hypoglycemia." (PMID 24833901, 2014). "GLP-1 drugs, in contrast to insulin, are devoid of risk for hypoglycemia and weight gain." (PMID 24423471, 2014). "Similarly, antidiabetic agents, including insulin and oral hypoglycemic agents were seen to cause hypoglycemia in this study." (PMID 24475089, 2014). "Indeed, strict glycaemic control using intensive insulin therapy increases the risk of hypoglycaemia threefold." (PMID 24607023, 2014). "Islet cell tumours of pancreas produce insulin which cause hypoglycemia." (PMID 24741994, 2014). "Moreover, GB markedly alters patterns of early postprandial glycemia, contributing to a potential mismatch between nutrient absorption and timing of prandial insulin, with risk of subsequent hypoglycemia." (PMID 24668543, 2014). "Diazoxide (DZD) is used to inhibit inappropriate insulin secretion, causing hypoglycemia." (PMID 24991532, 2014). "Thus, the action of incretin drugs as insulin secretagogues is more physiological than that of SUs, thereby resulting in a low risk of hypoglycemia and weight gain with incretin therapy." (PMID 26237486, 2014). "Conversely to insulin and other oral anti-T2D, the risk of hypoglycemia was also low and comparable between GLP-1R agonists and DPP-IV inhibitors, thereby constituting an additional advantage for their possible application in AD treatment, as further discussed in the next section." (PMID 25071725, 2014). "The fear of hypoglycemia might be higher in persons who are insulin dependent as the use of insulin is associated with increased episodes of hypoglycemia." (PMID 25241039, 2014). "In our study, the risk of hypoglycemia was lower because we utilized short insulin therapy." (PMID 25278226, 2014). "The counter-regulatory response to hypoglycemia could be also altered in patients who have had their CB removed, a status particularly critical in diabetic patients subjected to insulin treatment and therefore at high risk of hypoglycemia." (PMID 25360117, 2014). "No underlying autoimmune disorders or other causes of IAS could be identified, excluding the possibility that the hypoglycemia was caused by exogenous insulin increase." (PMID 25289063, 2014). "However, plasma concentrations of IGF-1 and IGF-2 can be 1000 times greater than insulin in NICTH allowing them to cause hypoglycemia." (PMID 24934576, 2014). "Pioglitazone sensitizes peripheral tissues to insulin and hence may cause hypoglycemia when insulin is used concomitantly, though hypoglycemia can also occur with monotherapy." (PMID 26556204, 2014). "Compared with T2DM patients initiated on insulin glargine in Turkey, insulin detemir was associated with a similar level of glycaemic control, but a lower risk of hypoglycaemia and greater odds of weight loss, after correction for a number of known confounders." (PMID 25048824, 2014). "Problems in treatment using sulfonylurea drugs and other existing oral antidiabetic agents or insulin typically include weight gain and hypoglycemia, but when incretin formulations are administered alone, the risk of weight gain and hypoglycemia is known to be low." (PMID 24578756, 2014). "A basal insulin analogue is employed as it would minimize the risk of hypoglycemia." (PMID 24886287, 2014). "Attempts to lower the postprandial glucose level by increasing the dose of basal insulin can lead to an increased risk of severe hypoglycemia during the night and early morning, which might also be associated with an increased risk of cardiovascular disease." (PMID 24684803, 2014). "A concern for an increased risk for hypoglycaemia with the intensive insulin treatment has emerged." (PMID 23663747, 2013).
Hypoglycemia (continued). "Meglitinides (or glinides) are short-acting secretagogues that stimulate insulin release through similar mechanisms to SUs, but may be associated with less hypoglycemia." (PMID 23841986, 2013). "The in silico results demonstrate that the proposed bihormonal AP systems have outstanding superiorities in reducing the risk of hypoglycemia, smoothing the glucose level, and robustness with respect to insulin/glucagon sensitivity variations, compared with the optimal unihormonal AP system." (PMID 24260042, 2013). "Insulin detemir was associated with a significantly lower risk of 24-h and nocturnal hypoglycaemia." (PMID 23094597, 2013). "In an effort to use regular insulin injections to maintain blood glucose levels within a normal range, patients with type 1 diabetes are continuously at risk of encountering episodes of recurrent/moderate hypoglycemia." (PMID 24278448, 2013). "However, the degree of systemic insulin therapy is limited by the risk of hypoglycemia; therefore, long term local delivery of insulin in the retina is needed to protect against neurodegeneration in DR." (PMID 23358247, 2013). "Such intensification of insulin regimens increases the risk of hypoglycaemia and may lead to weight gain which can increase cardiovascular risk and worsen weight-related comorbidities." (PMID 23061470, 2013). "It has been suggested that the reduced rate of hypoglycaemia observed with basal insulin analogues versus human insulins may be linked to improvements in HRQoL." (PMID 23451759, 2013). "Similarly, use of traditional combinations such as metformin with sulfonylureas, or metformin with insulin has limited clinical use owing to the associated hypoglycemia and weight gain." (PMID 23958390, 2013). "However, insulin has several disadvantages including multiple daily injections, the risk of hypoglycemia and maternal weight gain." (PMID 23724063, 2013). "Overproduction of insulin and associated hypoglycemia are hallmark features of this disease." (PMID 24455330, 2013). "Furthermore, the lower risk of nocturnal hypoglycemia with glargine and detemir has facilitated an earlier use of basal insulin in T2DM." (PMID 24348585, 2013). "However, strict glycaemic control and intensification of therapy can increase the risk of hypoglycaemia, especially for people treated with insulin or sulphonylureas." (PMID 23121373, 2013). "ExBID use is associated with a reduced incidence of nocturnal hypoglycemia compared with insulin." (PMID 23256660, 2013). "Furthermore, at equivalent levels of glycaemic control, insulin degludec demonstrates a lower risk of hypoglycaemia compared with insulin glargine 16,18–20." (PMID 23199058, 2013). "Notably, she had low insulin and C-peptide concentrations in the setting of hypoglycemia, which effectively excluded insulinoma, ectopic insulin production or exogenous insulin administration as the cause of hypoglycemia." (PMID 23302323, 2013). "However, in these studies, intensive insulin therapy was associated with an increased risk of hypoglycaemia and increased body weight." (PMID 23094597, 2013). "One explanation is that the reduced risk of hypoglycaemia with insulin detemir compared with traditional human insulin products may reduce the need for defensive snacking (over eating in order to try to prevent hypoglycaemic episodes)." (PMID 24499517, 2013). "Accordingly, the method might be a promising alternative strategy for treatment of DM given the adverse effects of insulin among patients, including the increased risk of modest weight gain and hypoglycemia." (PMID 23874448, 2013). "This preservation/improvement in the responsiveness of the beta cells in combination with exogenous insulin and improved insulin sensitivity could lead to increased risk of hypoglycemia." (PMID 22646230, 2012). "Hypoglycemia may also help explain why the introduction of an intensive insulin protocol has been associated with worse outcomes at some centers." (PMID 23082798, 2012).
Hypoglycemia (continued). "Overall, the elevated insulin sensitivity in dwarf Mbd5-deficient mice might contribute to the alteration of glucose homeostasis, resulting in hypoglycemia." (PMID 23077600, 2012). "With a basal-bolus insulin regimen, morning fasting hypoglycemia may be caused by the long- or intermediate- acting insulin; daytime hypoglycemia is implicated by rapid or short acting insulin; and nocturnal hypoglycemia may be implicated by either." (PMID 23497433, 2012). "Advancements in care, including multiple daily injection therapy with analog insulin, continuous subcutaneous insulin infusion, and continuous glucose monitoring, have each subsequently improved glycemic control and decreased the risk of severe hypoglycemia." (PMID 22716962, 2012). "The lower risk of hypoglycemia with liraglutide administration may be explained by its stimulation of insulin release and glucagon suppression in a glucose-dependent manner." (PMID 23153177, 2012). "In head-to-head randomised controlled trials (RCTs) of patients with T2DM, insulin glargine and NPH insulin resulted in similar glycaemic control (including HbA1c), although insulin glargine was associated with a significantly reduced risk of hypoglycaemia compared with NPH insulin." (PMID 22340448, 2012). "However, very intensive insulin regimens are associated with a higher risk of hypoglycaemia and weight gain, which can be a burden on patients." (PMID 22051096, 2012). "The release of insulin from the IAS insulin autoantibodies may cause hypoglycemia, and further studies are needed to explain why this type of autoantibodies may be related to hypoglycemia with no apparent loss of beta cells." (PMID 22567309, 2012). "This is supported by the observation that basal insulin, often judged easier to use and with less risk of hypoglycaemia, is seemingly preferred by general practitioners, in an office-based environment, and in urban locations, while premix is more widely used in specialist care." (PMID 22519930, 2012). "Determination of the risk of experiencing a hypoglycemic event by different categorizations of medications revealed a lower risk of hypoglycemia among those treated with oral agents only compared to those treated with insulin only (INT adjHR 0.53, 95%CI 0.36-0.78; STD adjHR 0.13, 95%CI 0.08-0.24)." (PMID 22646230, 2012). "Advancements in care, including multiple daily injection therapy with analog insulin, continuous subcutaneous insulin infusion, and continuous glucose monitoring, have each subsequently improved glycemic control and decreased risk of severe hypoglycemia." (PMID 22716962, 2012). "Thus, the dose of insulin can be optimized to balance the requirements of lowering blood glucose levels whilst reducing the risk of hypoglycemia." (PMID 22871230, 2012). "Impairments in hepatic glucose mobilization may be particularly important in individuals taking anti-diabetic medications that predispose the subject to hypoglycemia (e.g. sulfonylureas, insulin)." (PMID 22615911, 2012). "In particular, weight gain and increased hypoglycaemia are often associated with established glucose-lowering treatments that increase insulin secretion (in a glucose-independent manner) or insulin sensitivity and may heighten CV risk." (PMID 22234149, 2012). "Thus, it is of high clinical relevance to know that beyond insulin therapy, the most relevant factors associated with hypoglycemia were noradrenaline infusion, steroids and age." (PMID 21470423, 2011). "This suggests that the risk of hypoglycemia with AMG 837 may be lower compared with that of insulin secretagogues such as sulfonylureas that stimulate insulin secretion regardless of ambient glucose levels." (PMID 22087278, 2011). "However, a recently reported clinical trial of intensive insulin therapy (ACCORD) found a 3- to 4-fold increase in hypoglycemia which was associated with excess mortality." (PMID 22242020, 2011).
Hypoglycemia (continued). "In particular, adding insulin glargine to MET monotherapy was well tolerated and resulted in a significant proportion of patients achieving the glycaemic goal of HbA1c ≤7.0% with a low risk of hypoglycaemia and weight gain, in spite of a higher insulin dose used on average." (PMID 21481127, 2011). "Increasing the dosage of insulin units may be a solution to this problem; however, in practice, this can cause an increased risk of hypoglycemia and weight gain." (PMID 21443773, 2011). "B25Asp insulin could be administered at much higher doses, similar to those used in mice, while minimizing the risk of hypoglycemia." (PMID 21647401, 2011). "In support of this, meal studies with rye products in healthy adults demonstrated that a low insulin response was associated with less accentuated late postprandial hypoglycemia, lowered sense of hunger, and lowered late postprandial increase of plasma ghrelin." (PMID 21247415, 2011). "It remained unclear whether the increased susceptibility to severe hypoglycemia (glucose level ≤ 40 mg/dl) with intensive insulin therapy in sepsis patients was due to liver and renal dysfunction." (PMID 21470423, 2011). "The risk of hypoglycemia may be decreased with detemir, because of the flat and protracted pharmacodynamic profile compared to the peak in insulin activity seen with intermediate acting insulins." (PMID 22067102, 2011). "This is particularly important during fasting when inappropriate insulin secretion could cause life-threatening hypoglycemia." (PMID 21998599, 2011). "In the present study, the overall hypoglycemia rates observed with blood glucose concentrations < 40 mg/dl in 0.9% and < 80 mg/dl in 10.9% were low, furthermore the administration of insulin was associated with an increased risk of blood glucose concentrations < 80 mg/dl (OR 2.1; 95% CI 1.7 - 2.6)." (PMID 21470423, 2011). "Intensified lowering of blood glucose reduces the risk of chronic complications of type 1 diabetes; however, clinical attempts to achieve these benefits are limited by an increased risk of hypoglycemia induced by aggressive insulin therapy, also known as iatrogenic hypoglycemia." (PMID 22162752, 2011). "We have recently demonstrated that a product characterized by a low but prolonged blood glucose curve, described by a high Glycemic Profile (GP) was associated with lower insulin response, less postprandial hypoglycemia, and a smaller increase in late postprandial ghrelin." (PMID 21247415, 2011). "Moreover, there was a consistent and significant reduction in hypoglycaemia risk with insulin glargine compared with NPH insulin for both overall symptomatic (11%, p = 0.0006) and nocturnal (26%, p < 0.0001) hypoglycaemic events." (PMID 20618882, 2010). "While insulin has an essential role in the management of patients with insulin deficiency, its clinical use may lead to adverse effects such as hypoglycaemia and weight gain." (PMID 21274337, 2010). "Intensive glucose control--in particular when complex insulin strategies are used--is associated with a 5-fold increased risk for severe hypoglycemia, which could induce harm in some patients." (PMID 20843379, 2010). "Increased intra-patient variability with insulin therapy may increase the risk of hypoglycaemia, as was shown from a meta analysis and two further publications." (PMID 20618882, 2010). "All patients with DM who receive treatment with insulin, and certain patients treated with oral hypoglycemic agents that can cause hypoglycemia (essentially secretagogue drugs), need to have regular checks of glucose concentrations so as to maintain an appropriate metabolic control." (PMID 22163609, 2010). "Of particular importance when optimizing pharmacotherapy is the balance between optimal blood glucose adjustments (HbA1c, postprandial glucose) and the risk of hypoglycemia, the potential increase in body weight observed specifically with sulfonylureas, glinides and insulin regimens." (PMID 20843379, 2010).